MMP9 (matrix metallopeptidase 9)
Diseases named in the same sentence as MMP9 in open-access papers (continued):
Sharing a sentence is not in itself a finding about the gene and the disease.
asthma (continued). "The CTD database was used to predict the underlying therapeutic agents associated with asthma severity, and we noted that Reparixin may have great significance for precision treatment of asthma, targeting MMP9, CXCR1 and CXCR2." (PMID 38351296, 2024). "Notably, Reperixin displays the ability to target CXCR1, CXCR2, and MMP9, suggesting its potential therapeutic value for managing deteriorating asthma." (PMID 38351296, 2024). "Additionally, the expression of Il4 and neutrophilic inflammatory cytokines including Tgfb, Tnfa, Cxcl15, Elane, and Mmp9 in asthma exacerbation mice were markedly lower in LysMCreCul5fl/fl mice than in Cul5fl/fl mice." (PMID 38177117, 2024). "The expression of MMP-9 has been reported to be up-regulated in patients with asthma and COPD." (PMID 37959214, 2023). "Collectively, these findings suggest that oral disease may lead to the progression of respiratory disease, including asthma, via the hematogenous spread of MMP-9 from the periodontal tissues." (PMID 37959214, 2023). "MMP2 and MMP9 (gelatinases) are the most studied and well-characterized MMPs whose expressions and activations have been addressed in neoplastic pathologies and inflammatory disorders, including asthma." (PMID 37885469, 2023). "TGF-β increases the expression of ATRA and 9-cis RA in the ASM cells of patients with severe asthma compared with those with mild-to-moderate asthma, which results in upregulation of the mRNA of β1-integrin, MMP-9, and hepatocyte growth factor receptor (HGF-R)." (PMID 37367073, 2023). "In conclusion, our study shows that bergenin regulates the NF-κB pathway and blocks p65 translocation into the nucleus by activating SIRT1, thereby reducing the release of proinflammatory factors (such as IL-1β, IL-5, IL-6, and MMP-9 by macrophages) to play a role in asthma treatment." (PMID 36313381, 2022). "While Gelatinase B/MMP-9 rs3918249 SNP was connected to asthma and glaucoma." (PMID 36138580, 2022). "MMP-9 expression correlates with the severity of asthma and chronic obstructive pulmonary disease." (PMID 35169275, 2022). "In fact, low concentrations of LAS194046 combined with sub-effective concentrations of fluticasone propionate showed additive/synergic effects reducing IL-8, MMP9 and superoxide anion secretion in neutrophils from severe asthma and COPD patients, thus improving the corticosteroid insensitivity." (PMID 35332239, 2022). "MMP-9 and MMP-12 are increased in the airway smooth muscle of the large airways in fatal cases of asthma and it has been shown that HA may play a role in suppressing MMP9 production and be of potential therapeutic benefit." (PMID 34054525, 2021). "The increase in NF-κB phosphorylation not only elevates MMP-9 expression but also increases the production of cytokines, which, in turn, exacerbates airway inflammation in the lung tissue during the development of asthma." (PMID 34679759, 2021). "However, there is also some evidence that elevated IL‐17A increases the abundance of MMP‐9, an important tissue remodeling protein in asthma and late‐stage increases in IL‐17A concentration can induce apoptosis of neutrophils and eosinophils." (PMID 33747463, 2021). "Expression of MMP-9, however, is increased in both asthma and COPD, whereas the collagen IV α3 chain is only decreased in asthma, suggesting other proteases may also contribute to the degradation of collagen IV." (PMID 34877523, 2021). "MMP-9 seemed to be differentially released in exhaled condensates from asthmatics and based on this phenomenon, we can determine different biological phenotypes of asthma that can help to monitor diseases severity." (PMID 32054098, 2020). "Moreover, MMP-2 and MMP-9 activities have been found to participate in the progression of asthma and especially shown to be involved in matrix remodeling and inflammation." (PMID 33374928, 2020).
asthma (continued). "Notably, compared with asthma group, the Tetrandrine-treated group exhibited a prominent reduction of MMP-9 and TGF-β1 transcriptional level and a significant promotion of TIMP-1 mRNA." (PMID 31781316, 2019). "Indeed, one study showed a strong linkage disequilibrium between the −1562 C > T, rs3918242 polymorphism and 2127 G > T, rs2274755 polymorphism in the fourth intron, increasing the transcriptional level of MMP-9 and involving in the development of asthma." (PMID 30931075, 2019). "Taken together, MMP-9 may be an important factor involved in asthma, but the production of MMP-9 in chronic asthma with persistent airway obstruction is still undetermined." (PMID 31547356, 2019). "These accumulated data support the idea that MMP-9 plays an important role in asthma pathogenesis." (PMID 30931075, 2019). "After reading the abstracts and titles, 20 articles were subsequently excluded because they are review articles or not related the MMP-9 variants and asthma or not human studies." (PMID 30931075, 2019). "Increased levels and activities of matrix metallopeptidase (MMP)-2 and MMP-9 have been observed in sputum or BALF from asthma patients compared to those from controls, and these increases were proportional to the severity of the airway inflammation and the extent of airway remodeling." (PMID 31086415, 2019). "And MMP-9 is produced by epithelial and inflammatory cells and up-regulated release of matrix-associated TGF-β1, which promote pathological airway remodeling in patients with asthma." (PMID 31092255, 2019). "Similarly, alveolar macrophages released a higher amount of MMP-9 in chronic unstable asthma patients than those with stable asthma or normal subjects in our study." (PMID 31547356, 2019). "Additionally, increased levels of MMP-9 in serum, sputum, or lavage fluid were observed in patients with asthma." (PMID 31547356, 2019). "The persistently high levels of MMP-9 indicate that the remodeling of airways may be initiated at the beginning of asthma development and may be expressed as severe asthma." (PMID 31547356, 2019). "This means that persistent airway or lung inflammation of chronic unstable asthmatics may be less responsive to anti-asthma treatment, which may contribute to higher cellularity of inflammatory cells, thus leading to the increased amount of MMP-9." (PMID 31547356, 2019). "MMP-9-deficient animals could inhibit airway inflammation and the immunoreactivity of MMP-9 has also been reported to be correlated with asthma severity." (PMID 31547356, 2019). "Particularly, MMP-9 levels were clearly upregulated in different stages of equine asthma." (PMID 31316303, 2019). "Taken together, these results reveal that cigarette smoking may have association with an IL-17A-mediated inflammatory response and increased MMP-1 and MMP-9 expression in the nasal mucosa of patients with asthma and CRS." (PMID 31653934, 2019). "MMP9 is increased in human asthma, has anti-apoptotic effects in kidney injury and neutrophils and may be a link between inflammation and tissue remodeling." (PMID 28886691, 2017). "Finally, the authors refer to the studies on MMP-9 inhibition as a new perspective for increasing the effectiveness of treatment in asthma and COPD." (PMID 26123447, 2016). "The MMP-9 levels in patients with classic asthma are elevated in the serum, sputum, and BALF." (PMID 26783416, 2016). "In addition, IMD-4690 strongly inhibited airway remodeling by regulating the production of remodeling-related mediators (i.e., TGF-β, VEGF, and HGF) and enzymes (i.e., MMP9) in a chronic antigen exposure mouse model of asthma with Dp." (PMID 25785861, 2015). "In addition, neutrophil numbers and neutrophil inflammatory mediators such as CXCL8, NE, and MMP-9 are elevated in the airways of patients with severe asthma and these levels correlate with disease severity." (PMID 26663987, 2015).
asthma (continued). "Since patients with advanced asthma reveal increased concentration of MMP-9 in blood, sputum and bronchoalveolar lavage (BAL), it is assumed that MMP-9 may play the pivotal role in that remodeling." (PMID 25650123, 2015). "Mediators released by activated parenchymal and inflammatory cells could induce MMPs secretion and activation, increase in MMP-9 activity, and elevated MMP-9/TIMP-1 ratios as demonstrated in mild asthma after allergen challenge in sputum and BALF." (PMID 26770019, 2015). "Moreover, high MMP-9/EBC in asthma-suffering children significantly correlated with IgE serum levels." (PMID 25650123, 2015). "Therefore, the aim of the present study was to assess the amount and the actual activity of MMP-9 in EBC of asthma-suffering children, which were continuously treated with inhaled steroids." (PMID 25650123, 2015). "Asthma patients showed significantly elevated MMP-9 expression compared with the healthy controls." (PMID 26588845, 2015). "MMP-9 represents the largest and complex member of MMPs that is present in low quantities in the healthy adult lung but much more abundant in several lung diseases, including asthma, idiopathic pulmonary fibrosis, and RAO." (PMID 26770019, 2015). "In addition, MMP-9 induces the degradation of the extracellular matrix, resulting in airway remodeling in asthma." (PMID 26588845, 2015). "Matrix metalloproteinase (MMP)-9 is a protease that has been implicated in the pathogenesis of several well-recognized pulmonary disorders, including cystic fibrosis, acute lung injury (ALI), and asthma." (PMID 26264019, 2015). "Most recently, there have been reported increased MMP-9 levels in EBC of patients with asthma." (PMID 25650123, 2015). "Interestingly, we found similar neutrophil responses between patients with suboptimally controlled asthma and well-controlled asthma, particularly with deficient fMLF induced CXCL8 and MMP-9 release." (PMID 26663987, 2015). "Persistent MMP9 signaling is associated with tissue remodeling and the progression of many lung diseases including chronic obstructive pulmonary disease (COPD), asthma, airway infections and idiopathic pulmonary fibrosis." (PMID 26284919, 2015). "In severe asthma, increased basal levels of MMP-9 were even observed in plasma." (PMID 26770019, 2015). "Finally, we emphasize the necessity of further research focused on MMP-9 inhibition in asthma treatment." (PMID 25650123, 2015). "MMP9 appears to have important roles in asthma exacerbation and airway remodeling." (PMID 24904541, 2014). "Patients with asthma have increased MMP-9 levels in submucosal and epithelial areas." (PMID 24829780, 2014). "At a first glance, this finding may appear contradictory to previous speculations that the excess release of MMP-9 is involved in tissue remodelling in severe asthma and COPD." (PMID 24086430, 2013). "Of the MMP family, MMP-9 is the major proteinase that induces airway remodeling in asthma." (PMID 24073339, 2013). "In terms of the potential effects of MMP-9 on airway inflammation in asthma, in vitro studies have shown that MMP-9 may be important in mediating the migration of eosinophils across the basement membrane of blood vessels." (PMID 24223654, 2013). "Recently, it was reported that MMP-9 expression is increased in the bronchoalveolar lavage and lung tissue and overexpression of MMP-9 is upregulated in association with the accumulation of inflammatory cells in the airway in a murine asthma model." (PMID 23029210, 2012). "Therefore, we examined the anti-inflammatory effect of CP on Th2-type cytokines, eosinophil infiltration and other factors using an OVA-induced murine asthma model, and attempted to determine the possible role of MMP-9 in the protective effects of CP." (PMID 23029210, 2012). "Therefore, the control of nitric oxide synthase (NOS) and MMP-9 activities is an important aspect of asthma treatment." (PMID 23244755, 2012).
asthma (continued). "Furthermore, Pycnogenol, an anti-inflammatory drug is able to attenuate signs of inflammation in asthma patients through reduction of MMP-9 secretion." (PMID 20673327, 2010). "Eosinophils, important in asthma-related airway inflammation may also be a source of MMP9 and MMP9 expression correlate with eosinophil counts in bronchial mucosa." (PMID 20181264, 2010). "Our systematic study of MMP-9 variations suggests that polymorphisms in the MMP-9 gene have significant effects on non-atopic forms of asthma." (PMID 20181264, 2010). "Moreover, administration of VEGF receptor inhibitors reduced the pathophysiological signs of asthma and decreased the expression of MMP-9." (PMID 20920222, 2010). "In asthma MMP-9 is upregulated and involved in remodeling processes." (PMID 16441890, 2006). "As Pycnogenol has been reported to attenuate signs of inflammation in asthma patients we now provide first evidence that this anti-inflammatory in vivo effect might be at least partially attributed to reduced MMP-9 secretion on a molecular level." (PMID 16441890, 2006). "Additionally, p62 was inversely associated with minute ventilation, MMP‐9 inversely with FRC and bronchiolitis/asthma risk, while IFN‐γ and MMP‐9 was positively associated with lung clearance index, highlighting distinct protein–lung function and disease associations." (PMID 40952045, 2026). "Patients with COPD or asthma may experience hypoxia, which can alter their MMP-9 levels." (PMID 40117070, 2025). "Therefore, PAHs may contribute to asthma development and progression by modulating the MMP9 expression through gene body methylation." (PMID 41150507, 2025). "Overexpression of MMP9 in alveolar macrophages, bronchial tissues, sputum, and serum, has been previously associated with chronic obstructive pulmonary disease (COPD), emphysema, and asthma and upregulation of MMP9 in the blood has been associated with severe COVID-19." (PMID 36768847, 2023). "Apart from increase of MMP-9, tryptase stimulated cells also displayed a prominent pro-migratory effect; both are important features of normal physiological development and re-epithelialization upon injury but can also contribute to structural epithelial changes, which are observed in asthma." (PMID 36139491, 2022). "However, long-term or recurrent MMP-9 activation may result in airway injury or further aggravate airway remodelling in patients with COPD or asthma." (PMID 35892136, 2022). "Moreover, neutrophil-derived MMP-9 was elevated in patients with severe asthma." (PMID 36359917, 2022). "Thus, the maximal % inhibition of fluticasone propionate was 99.01 ± 2.26, 66.57 ± 7.45 and 50.77 ± 5.43 for IL-8 release in healthy, COPD and asthma neutrophils respectively, and 90.85 ± 7.66, 62.09 ± 3.79 and 42.72 ± 6.25 for MMP9 in healthy, COPD and asthma neutrophils respectively." (PMID 35332239, 2022). "Moreover, neutrophil-derived MMP-9 was increased in severe asthma." (PMID 34342773, 2022). "Meanwhile, NGF could aggravate asthma by increasing the level of MMP-9." (PMID 34502019, 2021). "In addition to inhibiting inflammatory cell infiltration in lung tissue, Lactobacillus GG was shown to decrease MMP9 expression, a class of enzymes that are involved in the degradation of the extracellular matrix and of which levels were significantly increased in asthma." (PMID 33799367, 2021). "Taken together, MMPs (mainly MMP-9) and TIMP-1 may contribute to progressive loss of lung function and increased cellular matrix fibrosis of the airway wall in chronic asthmatics who demonstrated a poor response to anti-asthma treatments." (PMID 31547356, 2019). "However, our study did not investigate the association of MMP-9 with M1/M2 polarization in the asthma with accelerated lung function decline." (PMID 31547356, 2019). "Therefore, MMP-9 level cannot be considered as a specific marker of COPD or asthma." (PMID 26123447, 2016).
asthma (continued). "Therefore, possibly the MMP-9 inhibition may be considered as a method of pharmacological prevention against respiratory tract remodeling in asthma." (PMID 25650123, 2015). "Therefore, MMP-9 is considered an important therapeutic target for the control of asthma." (PMID 26588845, 2015). "We hypothesize that MMP-9 hyperactivity in asthma may be closely related to high IgE serum levels." (PMID 25650123, 2015). "Therefore, although the exact role of MMP-9 in asthma still needs to be elucidated, the measurement of its activity in EBC may provide new data supporting the value of MMP-9 as indirect progression marker in the assessment of airway remodeling." (PMID 25650123, 2015). "Moreover, it has been found that MMP-9 levels correlated with severity of asthma symptoms." (PMID 25650123, 2015). "Moreover, MMP-9 alters the localization of tight junction components, such as claudin-1, occludin, and ZO-1, adversely affecting barrier function and eventually directly damaging respiratory epithelium in asthma." (PMID 24533168, 2014). "Furthermore, several studies have demonstrated the important role of MMP9 in classic asthma." (PMID 25187823, 2014). "Therefore, the role of elevated levels of MMP-9 in asthma may be related to TGF-β activation and its downstream fibrotic sequelae." (PMID 22315625, 2012). "Our results have shown that homozygocity for MMP-9 variants increase the risk to develop non-atopic forms of asthma and wheezing, which may be explained by a functional role of MMP-9 in airway remodeling." (PMID 20181264, 2010). "The very specific effects of genetic variations in the MMP-9 gene may help to dissect different forms of asthma and elucidate the diversity in the mechanisms leading to airway diseases such as non-atopic asthma and other common, non-atopic forms of childhood wheezing." (PMID 20181264, 2010). "As described in the features section, each disease class was mapped to literature-supported protein and gene expression profiles (MMP-9 and TGF-β for bronchiectasis, CRP and IL-6 for pneumonia, and IL-5 and YKL-40 for asthma)." (PMID 40806268, 2025). "Our results demonstrate that these phthalates affect the pathogenesis of asthma and COPD by modulating various target genes, including PTGS2, MMP9, and CASP3, which are involved in essential biological pathways such as apoptosis and immune response." (PMID 40160461, 2025). "In OVA-sensitised asthmatic rats, intraperitoneal injection of 5 mg TMP resulted in lower expression of both MMP-9 and TIMP-1 compared to the asthma model group." (PMID 40986971, 2025). "To further validate the anti-fibrotic properties of rosuvastatin treatment in asthma, we investigated two significant remodeling mediators: TGF-β and MMP-9." (PMID 38913666, 2024). "In our study, we employed a network pharmacology approach to prioritize seven predicted targets (AKT1, VEGFA, EGFR, SRC, MAPK3, MMP9, MAPK1) of baicalein for asthma treatment, and confirmed its high binding affinity to these targets through molecular docking." (PMID 38178132, 2024). "MMP-7, MMP-9, and MMP-10 are important in asthma, particularly in airway remodeling and extracellular matrix alterations." (PMID 38275403, 2024). "TIMP-1 antagonizes MMP-9 activity, and the finding of lower MMP-9/TIMP-1 ratios in the sputum of smokers with asthma suggests that excessive TIMP-1 production occurs as a defense against MMP-9 production in these patients." (PMID 36945930, 2023). "Recent studies have shown that patients with severe asthma and COPD have high levels of matrix metalloproteinase 9 (MMP-9) in sputum, and influenza A virus infection increases CD147 expression in lung cells in bronchial asthma patients." (PMID 36852336, 2023). "In obese mice, intraperitoneal administration of anti-TNF- monoclonal antibody significantly decreased lung matrix metallopeptidase 9 (MMP-9) activity, demonstrating a link between TNF- and increased asthma severity in obese subjects." (PMID 37251328, 2023).